SMARCA2 (SWI/SNF related BAF chromatin remodeling complex subunit ATPase 2)
Diseases named in the same sentence as SMARCA2 in open-access papers (continued):
Sharing a sentence is not in itself a finding about the gene and the disease.
lung adenocarcinoma (7 papers, 2018 to 2025). A carcinoma that arises from the lung and is characterized by the presence of malignant glandular epithelial cells. "Immunohistochemical analysis of 93 primary lung adenocarcinomas revealed loss of SMARCA2 and SMARCA4 in 17% and 12% of cases, respectively." (PMID 39888726, 2025). "(n=89), and multiplexed immunohistochemistry (IHC) staining of these two cases to decipher the poor prognosis dependent on the immunosuppressive barrier formed by FAP+ fibroblasts and SPP1+ macrophages in the SMARCA2-deficient while SMARCA4-preserved poorly differentiated lung adenocarcinoma (LUAD)." (PMID 40453096, 2025). "Moreover, SMARCA2 might be useful as a differential diagnostic indicator in primary lung adenocarcinoma, especially in TTF-1-negative tumors." (PMID 35289322, 2022). "The authors concluded that the loss of either or both SMARCA2 and SMARCA4 led to the progression of lung adenocarcinoma into a solid-predominant tumor and to epithelial–mesenchymal transition, with loss of the bronchial epithelial phenotype." (PMID 39888726, 2025). "In our study, SMARCA2-negative expression in lung adenocarcinoma was significantly associated with high-grade nuclei, acinar and papillary histological subtypes, and with solid and micropapillary histological subtypes." (PMID 35289322, 2022). "Meanwhile, Kaplan–Meier curve statistical analysis of the results for NSCLC and its two major subtypes, i.e., lung adenocarcinoma and lung squamous cell carcinoma, implies that SMARCA2 is a potential target for therapeutic use and a promising prognostic marker of NSCLC." (PMID 35289322, 2022). "It has also been shown that the likelihood of SMARCA2-negative expression is 2.427 times higher in TTF-1-negative lung adenocarcinomas than in TTF-1-positive lung adenocarcinomas." (PMID 35289322, 2022). "In both the major subtypes of NSCLC, lung adenocarcinoma and lung squamous cell carcinoma, the SMARCA2-negative group had a worse prognosis than the positive group." (PMID 35289322, 2022). "In 2174 lung adenocarcinomas, SMARCA2-negative expression (n = 205) was significantly correlated with high-grade nuclei, eosinophilic staining of the cytoplasm, solid and micropapillary histological subtypes, TTF-1-negative expression and Napsin-A-negative expression (P < 0.05)." (PMID 35289322, 2022). "Correlation of SMARCA2-negative expression with cytological features in lung adenocarcinoma." (PMID 35289322, 2022). "In lung adenocarcinomas, high-grade nuclei, histological morphology of acinar and papillary, solid and micropapillary and TTF-1-negative expression were relative risk factors affecting SMARCA2-negative expression." (PMID 35289322, 2022).
colorectal carcinoma (6 papers, 2011 to 2025). A malignant epithelial neoplasm that arises from the colon or rectum and invades through the muscularis mucosa into the submucosa. "In contrast, colorectal carcinoma with SMARCA2-deficient expression displays conventional gland-forming histologic features and is less likely to exhibit MMR deficiency." (PMID 38217014, 2024).
schizophrenia (6 papers, 2006 to 2025). A major psychotic disorder characterized by abnormalities in the perception or expression of reality. "In turn, the low SMARCA2 expression levels linked to this variant could be responsible for the increased risk of schizophrenia." (PMID 21070662, 2010). "First, genome-wide expression analysis of a post-mortem section of the dorsolateral prefrontal cortex of schizophrenia patients showed that SMARCA2 (also referred to as hSNFa) was upregulated 1.42-fold relative to non-affected controls." (PMID 16749937, 2006). "In addition, SMARCA2—the catalytic ATPase subunit of SWI/SNF—has been found to interact with the REST/NRSF complex and other schizophrenia risk genes." (PMID 40160416, 2025). "Smarca2 knockdown in cortical neurons results in abnormalities in neurite length and dendritic spines, morphological phenotypes that are characteristic of many NDDs, including schizophrenia." (PMID 40160416, 2025). "The SWI/SN subunit, BRM (SMARCA2), has been associated with self-reported MDD and schizophrenia." (PMID 35444632, 2022). "Another gene, SMARCA2, was also found to play a role in the pathophysiology of schizophrenia." (PMID 29257106, 2017). "Much evidence suggests that low levels of SMARCA2 may play a role in the pathophysiology of schizophrenia." (PMID 21070662, 2010). "Certain TFs such as ETS1, MAF, SMARCA2, TRPS1, and CREB3L1 appear to modulate TF-tagged genes in multiple traits, which could be key elements linking AD, bipolar disorder, and schizophrenia through shared regulatory pathways." (PMID 39905509, 2025).
squamous cell carcinoma (6 papers, 2020 to 2025). A carcinoma arising from squamous epithelial cells. "In an unselected series of NSCLC, loss of SMARCA4 and SMARCA2 was observed all together in 12% of adenocarcinomas (5.5% and 6.4%, respectively) compared to 6.9% (5.2% and 1.7%, respectively) of squamous cell carcinomas." (PMID 33506327, 2021). "They used Western blotting to demonstrate the molecular phenomenon in 30% of NSCLC cell lines and immunohistochemistry to show concomitant loss of SMARCA2 and SMARCA4 in 10% of primary NSCLC tumors across 41 adenocarcinoma and 19 squamous cell carcinoma (SCC) cases." (PMID 39888726, 2025). "However, in our study, most cases with SMARCA2-negative expression had adenocarcinoma or squamous carcinoma differentiation." (PMID 35289322, 2022). "Next, n = 116 samples of patients with pure squamous cell carcinoma (n = 68) and mixed urothelial carcinoma with substantial squamous differentiation (n = 48) were analyzed for seven SWI/SNF complex proteins (ARID1A, SMARCA4, SMARCB1, SMARCC1, SMARCC2, SMARCA2 and PBRM1) by immunohistochemistry." (PMID 33227989, 2020).
bladder cancer (5 papers, 2023 to 2025). "In bladder cancer, the level of SMARCA2 (encoding BRM protein) is significantly lower than that in normal tissues, and the low expression of SMARCA2 is associated with a poor prognosis in patients." (PMID 39779467, 2025). "The expression of BRM, which is encoded by the SMARCA2 gene, is closely related to the expression of the glycolytic enzyme pyruvate kinase M2 (PKM2) and the AMPKα1-encoding gene (PRKAA1) in bladder cancer cells." (PMID 39609317, 2024). "One study revealed that in patient-derived bladder cancer tumors, dysregulation of several SWI/SNF subunits (SMARCA2, INI1 and BAF155) again correlated with alterations in expression of genes involved in glucose metabolism." (PMID 38666605, 2024). "The expression of SMARCA2 is closely related to the expressions of pyruvate kinase M2 (PKM2) and protein kinase AMP‐activated alpha 1 catalytic subunit (PRKAA1) genes as well as metastasis, which suggests that metabolic alterations exist in bladder cancer." (PMID 39779467, 2025). "Additionally, the expression of SMARCA2 influences the expression of Fructose‐1,6‐bisphosphatase 1 (FBP1), and the low expression of FBP1 is related to the clinical stage of bladder cancer, more frequent recurrence, and metastasis." (PMID 39779467, 2025). "However, unlike the previous two studies carried out in different cell types, this study found that low expression of the ATPase SMARCA2 (BRM) was found to increase expression of the glycolytic enzyme pyruvate kinase M2 (PKM2), and this correlated with bladder cancer metastasis." (PMID 38666605, 2024).
gastric cancer (5 papers, 2019 to 2025). A primary or metastatic malignant neoplasm involving the stomach. "SMARCA2 gene mutations were also identified in about 10% of gastric cancers." (PMID 31722744, 2019). "In contrast, the loss of SMARCA2 and SMARCA4 resulted in worse survival, implicating the essential role of the two subunits in undifferentiated/dedifferentiated gastric carcinoma." (PMID 36464671, 2022). "In about 10% of gastric cancers, methylation of SMARCA2 promoter region was identified." (PMID 31722744, 2019). "Especially with regard to a possible determination of SWI/SNF status in routine diagnostics, it seems reasonable to limit the determination of SWI/SNF status in gastric cancer to SMARCA4, SMARCA2, and ARID1A." (PMID 34359794, 2021). "Meanwhile, considering the poor prognosis of undifferentiated/dedifferentiated gastric carcinoma, it is recommended to carry out immunohistochemical examinations of SWI/SNF complex subunits, especially SMARCA2 and SMARCA4, further to implement stratification for precise and individualized treatment." (PMID 36464671, 2022).
glioma (5 papers, 2020 to 2025). A benign or malignant brain and spinal cord tumor that arises from glial cells (astrocytes, oligodendrocytes, ependymal cells). "We demonstrate that H3K27M gliomas show increased protein levels of the SWI/SNF complex ATPase subunits SMARCA4 and SMARCA2, and the PBAF component PBRM1." (PMID 37094128, 2023). "We demonstrate that a PROTAC tool compound AU-15330 that simultaneously degrades the ATPases SMARCA4 and SMARCA2 and PBRM1 selectively kills H3.3K27M but not H3WT glioma cell lines." (PMID 37094128, 2023).
triple-negative breast carcinoma (5 papers, 2016 to 2022). An invasive breast carcinoma which is negative for expression of estrogen receptor (ER), progesterone receptor (PR), and human epidermal growth factor receptor 2 (HER2). "Additionally, it was observed that both BRG1 and BRM are required for the triple-negative breast cancer (TNBC) proliferation and that double SMARCA2 and SMARCA4 knock-down results in slowed tumour growth in xenografts." (PMID 31722744, 2019).
uveal melanoma (5 papers, 2021 to 2024). A melanoma derived from melanocytes of the uveal tract. "Uveal melanoma is another cancer type that is highly sensitive to treatment with allosteric SMARCA4/SMARCA2 inhibitors." (PMID 38390898, 2024). "Some uveal melanoma cell lines were highly sensitive to the depletion of SMARCA4 alone and others were only sensitive to the dual depletion of both SMARCA4 and SMARCA2." (PMID 38390898, 2024). "SMARCA2/4 ATPase antagonists are currently in phase I clinical trials for SMARCA2/4-dependent cancers, such as uveal melanoma and acute myeloid leukemia (NCT04879017 and NCT04891757) highlighting the feasibility of this approach." (PMID 36894709, 2023). "Recently, SF3B1 mutations in uveal melanoma (UVM), myelodysplastic syndrome (MDS), and CLL were associated with mis-splicing of Bromodomain Containing 9 (BRD9), a subunit of the non-canonical BRG1 (SMARCA4) or BRM (SMARCA2) associated factor (ncBAF) chromatin remodeling complex." (PMID 39261602, 2024).
acute myeloid leukemia (4 papers, 2021 to 2025). Acute myeloid leukemia (AML) is a group of neoplasms arising from precursor cells committed to the myeloid cell-line differentiation. "Acute myeloid leukemia (AML) cells were found to be highly sensitive to allosteric SMARCA4/SMARCA2 inhibitors, BRM011 and BRM014." (PMID 38390898, 2024). "SMARCA2/4 (BRM/BRG) have been widely studied; SMARCA4 is frequently mutated in cancer and maintains oncogenic transcription and cellular proliferation in acute myeloid leukemia (AML)." (PMID 34298819, 2021).
clear cell renal cell carcinoma (4 papers, 2018 to 2025). "Previous studies have established that SMARCA2 deficiency is a pathognomonic genomic driver in high-grade clear cell renal cell carcinoma (ccRCC), mechanistically linked to epigenetic reprogramming that fuels sarcomatoid differentiation." (PMID 41312169, 2025). "The loss of chr 9p, the SMARCA2 gene location, was associated with aggressiveness in clear cell renal carcinoma and is used as a prognostic marker." (PMID 33931971, 2021). "Similarly, decrease of overall survival in SMARCA2 negative tumors has been also recently reported in clear cell renal cell carcinoma but only when levels of PBRM1 protein, another subunit of the SWI/SNF complex were also reduced." (PMID 29391527, 2018).
epilepsy (4 papers, 2017 to 2023). A brain disorder characterized by episodes of abnormally increased neuronal discharge resulting in transient episodes of sensory or motor neurological dysfunction, or psychic dysfunction. "We conclude that (i) NBCRS spectrum features can be caused by mutations outside the ATPase region of SMARCA2; and that (ii) the epilepsy phenotype in NBCRS can be consistent with MAE syndrome." (PMID 27665729, 2017). "Interestingly, among multiple CRF genes, only SMARCA2, SMARCB1, ACTL6B and KDM5C have been previously associated with epilepsy, and some other members of this cluster (e.g., SMARCC1, SMARCC2, SMARCA4 and WRD5) are only cursorily mentioned among epilepsy candidate genes." (PMID 36982355, 2023).
epithelioid sarcoma (4 papers, 2021 to 2025). An aggressive malignant neoplasm of uncertain differentiation, characterized by the presence of epithelioid cells forming nodular patterns. "However, epithelioid sarcoma is SMARCB1-deficient with retained SMARCA2 expression, and the expression of SOX2 and SALL4 is deficient." (PMID 38347129, 2024). "In particular, the SWI/SNF subunit SMARCB1 has been approved as an effective marker of metastatic or locally advanced epithelioid sarcoma sensitivity to tazemetostat, while SMARCA2, SMARCA4, ARID1A, and PBRM1 are potential marker candidates." (PMID 34202528, 2021). "The catalytic ATPase subunit SMARCA2 (BRM) was absent in all lines except VA-ES-BJ (epithelioid sarcoma), while SMARCA4 (BRG1) was detected in all lines except CHLA-06-ATRT (rhabdoid tumour)." (PMID 37236926, 2023).
multiple myeloma (4 papers, 2022 to 2025). "Physical and functional interactions between NSD2 and other chromatin regulators, such as EZH2 and SMARCA2, further reprogram the chromatin landscape, promoting myeloma growth, altering enhancer activity, and sustaining drug resistance." (PMID 40563566, 2025).
viral infection (4 papers, 2018 to 2025). "In summary these data confirm that SMARCA2 is required for efficient antiviral activity of MxA in the context of an H5N1 wild type virus infection." (PMID 29391557, 2018). "From this, it can be seen that STAG2 and SMARCA2, while both being regulated by the same miRNA, potentially have directly contrasting roles, with one being antiviral (SMARCA2) and the other supporting viral infection (STAG2)." (PMID 40981223, 2025). "Furthermore, the identification of STAG2 and SMARCA2 was further highlighted by their role in other viral infections." (PMID 40981223, 2025). "After this screening, four genes (STAG2, CD40LG, SMARCA2 and OLFML3) were found to have predictively high scores from the databases and their established links to the immune response and viral infection." (PMID 40981223, 2025). "Differentially expressed genes in the viral infection category (174 genes) indicated that keratinocytes had down-regulated genes involved in host gene transcription (DDX56, SMARCA2) and RNA transportation and processing (NUP98, RAE1, XAB2, RBM17, EXOSC10)." (PMID 34552595, 2021).
adenoid cystic carcinoma (3 papers, 2019 to 2025). A malignant tumor arising from the epithelial cells. "Somatic mutations in SMARCA2 have been reported in chronic lymphocytic leukemia and, most typically, in adenoid cystic carcinoma." (PMID 34874980, 2021).
Blepharophimosis (3 papers, 2023 to 2025). A fixed reduction in the vertical distance between the upper and lower eyelids with short palpebral fissures. "Mutations in SMARCA2 were reported in developmental syndromes that involved CHD, including Nicolaides–Baraitser syndrome (#MIM 601358) and blepharophimosis intellectual disability syndrome." (PMID 41427249, 2025).
blepharophimosis-impaired intellectual development syndrome (3 papers, 2023 to 2025). "Heterozygous pathogenic variants in SMARCA2 are associated with Blepharophimosis-impaired intellectual development syndrome or with Nicolaides–Baraitser syndrome." (PMID 40725402, 2025). "In the second example, variants in SMARCA2 cause two disorders, Nicolaides–Baraitser syndrome (NCBRS; OMIM #601358) and Blepharophimosis-impaired intellectual development syndrome (BIS; OMIM #619293)." (PMID 40280028, 2025).
breast tumors (3 papers, 2013 to 2023). "In some tumor types, namely lung, kidney, and breast tumors, the event of SMARCA2 downregulation occurs during cancer de-differentiation (disease progression), suggesting a clonal selection of SMARCA2-abrogated cancer cells." (PMID 36674511, 2023). "For example, the exploration of the SWI/SNF complex in breast tumors revealed that ARID1A tends to be mutated in samples where neither SMARCA4, ARID2 nor SMARCA2 are mutated." (PMID 24063517, 2013).
cervical cancer (3 papers, 2015 to 2020). A primary or metastatic malignant neoplasm involving the cervix. "Genes PFDN4, CASP1, PLCE1, ICOSLG, GADD45G, SMARCA2, and TSPO are located in different chromosomes, and there are reports for changes in each one of these chromosomes in cervix cancer, for examples the reader is refer to:." (PMID 26388997, 2015).
colon carcinoma (3 papers, 2018 to 2021). "In fact, high expression of SMARCA2 was associated with poor prognosis only in colon carcinoma." (PMID 29391527, 2018).
endometrial carcinoma (3 papers, 2019 to 2025). A malignant tumor arising from the epithelium that lines the cavity of the uterine body. "Dual loss of both the SMARCA4 and the SMARCA2 occurs in SCCOHT and in other neoplasms such as thoracic sarcomas, undifferentiated and dedifferentiated endometrial carcinomas, and rare undifferentiated uterine sarcomas." (PMID 35200537, 2022).
esophageal adenocarcinoma (3 papers, 2017 to 2025). A malignant tumor with glandular differentiation arising predominantly from Barrett mucosa in the lower third of the esophagus. "Almost nothing is known about the other familiar members of the SWI/SNF complexes, SMARCA2 (BRM), SMARCA4 (BRG1) and SMARCB1 (INI1), in oesophageal adenocarcinoma (EAC)." (PMID 31906887, 2020).
esophageal squamous cell carcinoma (3 papers, 2019 to 2025). Esophageal squamous cell carcinoma (ESCC) is a type of esophageal carcinoma (EC) that can affect any part of the esophagus, but is usually located in the upper or middle third. "In contrast, SMARCA4 loss inhibits the growth of acute myeloid leukemia cells, melanoma, and SMARCA2-deficient esophageal squamous cell carcinoma (ESCC)." (PMID 36633435, 2023). "Using CRISPR-Cas9 screening, we identify SMARCA4 as a novel dependency in SMARCA2-deficient esophageal squamous cell carcinoma (ESCC) models, reciprocal to the known synthetic lethal interaction." (PMID 31406271, 2019).
sarcoma (3 papers, 2023 to 2025). A usually aggressive malignant neoplasm of the soft tissue or bone. "Similarly, the expression levels of SWI/SNF-related genes, such as SMARCB1, SMARCA2, and SMARCA5-AS1 also seemed to be differentially expressed in MFS/US sarcomas." (PMID 37185612, 2023).